CDH1 (cadherin 1)
Diseases named in the same sentence as CDH1 in open-access papers (continued):
Sharing a sentence is not in itself a finding about the gene and the disease.
bladder cancer (220 papers, 1995 to 2026). "The inhibitory effect of CTNNA1 in bladder cancer was implicated in enhancing CDH1 expression and inhibiting EMT." (PMID 36741258, 2023). "It was further observed that EGF and CDH1 in the PPI network were annotated as being bladder cancer-associated proteins, and both receptor FGFR2 and PDGFRB could interact with EGF." (PMID 24801713, 2014). "In this way, SNHG1 enhances EZH2 expression in the nucleus to down-regulate CDH1, resulting in a decrease in E-cadherin levels and promoting metastasis and migration of bladder cancer cells." (PMID 35236381, 2022). "CDH1 overexpression inversely correlated with immune infiltration in bladder cancer." (PMID 38767825, 2024). "In the case of bladder cancer, loss of E-cadherin expression is a common event, which occurs in advanced tumours as a result of CDH1 locus hypermethylation or mutation and there is evidence for a strong association between hypermethylation of the E-cadherin locus with high disease-progression risk." (PMID 21049033, 2010). "In our study, SCAMP2 overexpression was found to promote the EMT process, evidenced by the downregulation of the epithelial marker CDH1 and the upregulation of the mesenchymal marker CDH2, thereby enhancing cisplatin resistance in bladder cancer." (PMID 40406117, 2025). "Next, we performed the survival analysis of these eight genes (ACTA2, CDH1, CCNB1, FLNA, MCM5, MAD2L1, TAGLN and TPM1) in bladder cancer." (PMID 37274283, 2023). "CTNNA1 enhances the expression of CDH1 and inhibits the expression of CDH2, SNAI1, MMP2, and MMP9 in bladder cancer cells." (PMID 36741258, 2023). "We also detected some biological markers in the diagnosis of recurrent bladder cancer was dysregulated in UCB, including KRT20 (Cytokeratin 20), BIRC5 (Survivin), CDH1 (E-cadherin) and PSCA (Prostate Stem Cell Antigen-14)." (PMID 24622401, 2014). "We chose five candidate genes (PTPRF, MMP2, VEGFA, CDH1 and CLDN7) that were detected differential expression by Cuffdiff and involved in Bladder cancer pathway, cell adhesion molecules (CAMs) pathway and focal adhesion pathway." (PMID 24622401, 2014). "CDH1 and SFN genes were methylated at high frequencies in bladder cancer as well as in paired normal adjacent tissue and exfoliated cells from cancer-free patients." (PMID 18702824, 2008). "In the CENPA knockdown cells, the epithelial marker CDH1 and cell senescence marker p21 were significantly upregulated, while the mesenchymal marker CDH2 was downregulated, while CENPA overexpression can significantly inhibit the damage of MAP30 to bladder cancer cells." (PMID 40804263, 2025). "Additionally, we examined the effects of siRNA-induced suppression of CDH1 CDH3 expression in a bladder cancer cell line model 5637, which, unlike the RCC cell line used in our study, shows substantial endogenous CDH3 expression." (PMID 38003666, 2023). "Overall, these observations suggest that both genes, CDH1 and SFN, are not effective biomarkers for MSP analysis in bladder cancer." (PMID 18702824, 2008). "Indistinct DNA hypermethylation of CDH1 and SFN genes between tumoral and normal urinary bladder samples suggests that these epigenetic features are not suitable biomarkers for urinary bladder cancer." (PMID 18702824, 2008).
cervical carcinoma (200 papers, 2005 to 2026). A carcinoma arising from either the exocervical squamous epithelium or the endocervical glandular epithelium. "Promoter hypermethylation of P16, DKAP, CDH1 and other related tumor suppressor genes was linked to clinical pathological parameters in cervical cancer." (PMID 24551169, 2014). "For instance, altered methylation levels of CDH1 (Cadherin 1), whose loss contributes to cancer progression by increasing proliferation, invasion, and/or metastasis are recorded in oral cavity, oral, and in cervical cancer." (PMID 32961999, 2020). "In univariate and multivariate analyses, patients with cervical cancer with unmethylated CDH1/CDH13 in serum had significantly better DFS." (PMID 38110977, 2023). "Tian et al30 identified that the cervical cancer patients with five notable nonsynonymous mutant genes (PIK3CA, BRAF, GNA11, FBXW7, and CDH1) metastatic relapse significantly mutated mutations had significantly poor DFS and OS." (PMID 35762423, 2023). "CDH1 is considered a tumor suppressor gene and is frequently silenced by the methylation of its promoter in cervical cancer and other human tumors." (PMID 34991696, 2022). "Promoter methylation of the E-cadherin gene (CDH1) was tested in combination with cadherin 13 (CDH13) in serum samples of 93 cervical cancer patients." (PMID 35725812, 2022). "It has been reported that CBX7 hinders HDAC2 activity to promote CDH1 expression and block epithelial-mesenchymal transition in thyroid, pancreatic and cervical cancer cells 19, 22-24." (PMID 35342353, 2022). "Conversely, expression of the epithelial markers E-cadherin (CDH1) and ZO-1 (TJP1) was increased, suggesting that JNK/c-Jun activity is required for the invasive potential of cervical cancer cells, potentially through the regulation of EMT-associated proteins." (PMID 33303976, 2021). "E-cadherin, (CDH1) is a fundamentally important gene that limits migration and is reported to be methylated in cervical cancer." (PMID 31766427, 2019). "Based on our findings, we propose two different mechanisms for the involvement of miR-9-5p in the induction of EMT in cervical cancer: In SCC, abundance of miR-9-5p caused by a chromosomal gain of 1q leads to degradation of both TWIST1 and CDH1." (PMID 31888045, 2019). "Western blot analysis showed that overexpression of TFF3 repressed E-cadherin (CDH1) expression to promote the invasion of cervical cancer cells." (PMID 28070169, 2017). "Our data suggested that TFF3 stimulated an invasive phenotype in cervical cancer cells through STAT3 mediated repression of CDH1." (PMID 28070169, 2017). "Conversely, TFF3 knockdown in two cervical cancer cell lines increased CDH1 expression mRNA level with concomitant decrease of phosphorylation of STAT3." (PMID 28070169, 2017). "Also, SOX1 increases the expression of CDH1, leading to the suppression of cell growth and invasiveness of cervical cancer." (PMID 38675711, 2024). "CDH1 shows the correlation with cervical cancer carcinogenesis as well as histological subtypes." (PMID 35057823, 2022). "The study could show a better clinical outcome of cervical cancer patients with unmethylated CDH1/13 compared to patients with the methylated genes (median disease-free survival for CDH1/13 unmethylated: 4.3 years, methylated: 1.2 years)." (PMID 35725812, 2022). "The EZH2-Binding lncRNA in cervical cancer, EBIC, (also known as thymopoietin pseudogene 2, TMPOP2), may promote motility and invasion of cervical cancer cells by repressing CDH1 (E-Cadherin) expression though EZH2." (PMID 32326624, 2020). "In cervical cancer, downregulation of CDH1 has been observed." (PMID 31888045, 2019). "Moreover, we observed that TFF3 repressed the expression of CDH1 to promote cell invasion in cervical cancer cells." (PMID 28070169, 2017). "This highlights the potential overestimation of CDH1 methylation frequency in cervical cancer." (PMID 25826459, 2015).
cervical carcinoma (continued). "Also in paclitaxel-resistant cervical cancer, miR-375-3p targeting CDH1 mRNA encoding E-cadherin was found to be up-regulated, therefore miR-375-3p may facilitate the EMT process of cervical cancer cells." (PMID 35922756, 2022). "However, it was validated that CDH1 methylation analysis in serum samples may be of potential use as a prognostic marker for cervical cancer patients." (PMID 22942707, 2012). "However, it was shown that CDH1 DNA-methylation analysis may be of potential use as a prognostic marker for cervical cancer patients." (PMID 22942707, 2012). "In cervical cancer, the PRMT5–SNAIL–NuRD complex suppresses cadherin 1 (CDH1: also known as E-cadherin) and ten–eleven translocation methylcytosine dioxygenase 1 (TET1) gene expression by binding to their promoter regions." (PMID 36980950, 2023). "The expression of E-cadherin, DAPK1, RARβ, p16INK4a, MGMT, FHIT, RUNX3, CDH1, PTEN, and SOC51 was also reactivated through genistein-induced promoter hypomethylation in cervical cancer cells." (PMID 32878338, 2020). "In the cervical cancer (HELA) cell line, EGCG (25 μM) suppressed DNMT3B activity and expression, leading to promoter hypomethylation and the reactivation of RARβ, CDH1, and DAPK1." (PMID 32878338, 2020). "Genes encoding several key regulators of the oncogenic Wnt/β-catenin pathway, such as CDH1 (E-cadherin), APC, and WIF1, are frequently silenced via dense methylation of their promoter regions in cervical cancer." (PMID 25826459, 2015). "We confirmed that DAPK1, RARB, SLIT2, and WIF1 are aberrantly methylated in cervical cancer compared to normal tissue, whereas, APC, CDH1 and FHIT are less commonly methylated." (PMID 25826459, 2015). "In the present study, we investigated the DNA-methylation status of CDH1 and CDH13 in serum samples from 49 cervical cancer patients and 40 patients with benign diseases." (PMID 22942707, 2012). "DNA-methylation status of CDH1 and CDH13 was analyzed by means of MethyLight-technology in serum samples from 49 cervical cancer patients and 40 patients with diseases other than cancer." (PMID 22942707, 2012). "For example, genes involved in cell cycle (p16), apoptosis (DAPK), cell adherence (CDH1), DNA repair (MGMT), and APC/β-cateninroute (APC) were found to be aberrantly methylated in cervical cancer." (PMID 16928264, 2006). "Moreover, HPV+/EBV+ cervical cancer displays increased RB1 and E-cadherin (CDH1) gene promoter methylation compared with HPV+/EBV− tumors." (PMID 32839399, 2020). "As it is reported CDH1 and CDH13 methylation in serum can be considered as cervical cancer markers." (PMID 31191840, 2019). "To investigate whether the direct interaction between miR-9-5p and TWIST1 can (partly) explain the different role of miR-9-5p in cervical SCC and AC, we analyzed expression of CDH1 and CDH2 in cervical cancer cells." (PMID 31888045, 2019). "CDH1 is a downstream protein of TFF3 and may be a key modulator of TFF3-mediated cervical cancer invasion." (PMID 28070169, 2017). "The methylation status of both genes increased with disease progression, showing the lowest frequencies in the control (6.7% for RB1 and 13.3% for CDH1) and LSIL samples (5.8% for RB1 and 11.8% for CDH1) and the highest in cervical cancer samples (50.0% for RB1 and 33.3% for CDH1)." (PMID 26032781, 2015). "From the findings of this study, we conclude that serological detection of CDH1 or CDH13 promoter hypermethylation is not able to predict invasive cervical cancers." (PMID 22942707, 2012). "This study was designed to investigate the DNA-methylation status of E-cadherin (CDH1) and H-cadherin (CDH13) in serum samples of cervical cancer patients and control patients with no malignant diseases and to evaluate the clinical utility of these markers." (PMID 22942707, 2012).
cervical carcinoma (continued). "Recently, we identified CDH1 and CDH13 DNA-methylation in serum samples taken at the time of diagnosis as an independent prognostic marker in cervical cancer patients with no concurrent chemo- or radiation therapy." (PMID 22942707, 2012). "Furthermore, based on the GSE168652 dataset of single‐cell RNA sequencing results of human cervical cancer tissues, we recognized six cancer cell subclusters, which were characterized by negative PTPRC (a marker of immune cells) and positive CDH1, CDKN2A, and EPCAM (markers of epithelial cells)." (PMID 36999964, 2023).
glioma (197 papers, 2010 to 2026). A benign or malignant brain and spinal cord tumor that arises from glial cells (astrocytes, oligodendrocytes, ependymal cells). "As the grade of glioma decreased, so did the number of cases in which CDH1 was mutated; thus, anaplastic oligodendrogliomas harbored 1.16% and anaplastic astrocytomas 1.01%." (PMID 40679044, 2025). "In summary, rare variants in the tumor suppressor gene CDH1 were significantly more frequent in the germline of glioma families (13.3%) compared to controls (1.7%)." (PMID 33929593, 2021). "Our data suggest an association of rare CDH1 variants with the risk of brain tumors, particularly of gliomas, and with the tumorigenesis of ODs." (PMID 33929593, 2021). "As four of the five patients in our two glioma families carrying rare CDH1 germline variants were affected by ODs, we investigated the frequency of CDH1 variants in tumor DNA of a cohort of ODs, WHO grade II/III." (PMID 33929593, 2021). "The potential pathogenicity of the rare CDH1 variants identified in glioma families 1 and 2 was investigated using several in vitro and computational models." (PMID 33929593, 2021). "In an effort to elucidate the underlying molecular mechanism of miR-92a-3p in glioma cells and GSCs, we applied bioinformatics and predicted that CDH1 and Notch-1 are the potential target genes of miR-92a-3p." (PMID 27801803, 2016). "More specifically, our data imply that ODs are the brain tumors most likely to occur in the presence of a rare CDH1 germline variant, because this tumor type was observed in four of five tumor patients carrying rare CDH1 germline variants of two glioma families here." (PMID 33929593, 2021). "To assess the consequences of the two rare CDH1 germline variants, c.1774G > A p.(A592T) and c.2450C > T p.(A817V), identified in glioma families 1 and 2, we performed functional analyses using two cellular models, i.e. CRISPR/Cas9-mediated HEK293T knock-in and stably transfected CHO cells." (PMID 33929593, 2021). "Furthermore, we propose that pharmacologically targeting WNT/β-catenin signaling by MNK1 inhibitors may have prophylactic or therapeutic potential specifically in (oligodendro)glioma patients harboring CDH1 variants affecting this pathway." (PMID 33929593, 2021). "Therefore, sensitizing gliomas with MNK1 inhibitors prior to e.g. temozolomide treatment may be particularly effective in glioma patients carrying CDH1 variants affecting WNT/β-catenin signaling." (PMID 33929593, 2021). "In gliomas, CDH1 expression is low or unexpressed due to hypermethylation and decreases with increasing GBM stage." (PMID 40725030, 2025). "The circRNA, termed circE-Cad, is generated from the E-cadherin locus (CDH1) and is upregulated in glioma stem cells and glioma tissues compared to controls." (PMID 35269953, 2022). "Very recently, a few studies have explored other tumor-promoting changes that occur in cancers with ATRX deficiency, including increased cellular motility in glioma cells and TGF-β activation with CDH1 (E-cadherin) downregulation in liver cancer cells." (PMID 36073547, 2022). "All brain tumors in CDH1-mutant glioma families were oligodendroglial tumors, and rare CDH1 variants were detected in the tumor DNA of 6% of ODs, WHO grade II/III." (PMID 33929593, 2021). "Subsequent mechanistic investigation indicated that cadherin 1 (CDH1)/β-catenin signaling and Notch-1/Akt signaling were the downstream pathways of miR-92a-3p in glioma cells and GSCs, respectively." (PMID 27801803, 2016). "In glioma cells, CDH1 expression was elevated after being transfected with an over-expressed plasmid containing only the coding region of CDH1." (PMID 27801803, 2016). "Mechanically, we demonstrated that miR-92a-3p targeted CDH1/β-catenin signaling in glioma cells, while Notch-1/Akt signaling was the downstream pathway of miR-92a-3p in GSCs." (PMID 27801803, 2016).
glioma (continued). "The data suggested that down-regulation of miR-92a-3p result in a robust increase of mRNA and protein levels of CDH1 in glioma cell, whereas up-regulation of miR-92a-3p induced a considerable decrease in the mRNA and protein levels of Notch-1in GSCs." (PMID 27801803, 2016). "Collectively, these data demonstrated that miR-92a-3p targeted CDH1/β-catenin and Notch-1/Akt signaling pathways in glioma cells and GSCs, respectively." (PMID 27801803, 2016). "CTNNB1 controls the expression levels of CDH1 (E-cadherin) to mediate cellular attachments and is often over-expressed in high grade glioma when compared to low grade or normal tissue." (PMID 24672773, 2014). "Because conventionally cultured cell lines are more easily manipulated, a panel of nineteen conventionally cultured glioma cell lines was screened by Western blot for the presence of E-cadherin, N-cadherin, cadherin-11, β-catenin, and p120 catenin." (PMID 21060868, 2010). "Thus, rare CDH1 germline variants predicted to be deleterious co-segregated with the tumor phenotype, mostly with ODs, WHO grade II/III, in two of 15 (13.3%) glioma families, and their frequency was significantly lower in controls (1.7%)." (PMID 33929593, 2021). "Moreover, in a series of low-grade gliomas, CDH1 promoter methylation status was found to be frequent (65% astrocytomas, 66% oligodendrogliomas, and 57% oligoastrocytomas) and hypermethylation status associated with shorter progression-free survival." (PMID 34680444, 2021). "Considering the tumor types observed in our glioma families, recommending prophylactic total gastrectomy as an option, as is done in carriers of unequivocally pathogenic CDH1 variants, does not seem appropriate." (PMID 33929593, 2021). "Taken together, the frequency of rare non-silent CDH1 germline variants predicted to be deleterious was significantly increased in our cohort of glioma families (2/15, 13.3%) compared to controls from the gnomAD v2.1.1 dataset (1.7%)." (PMID 33929593, 2021). "As the two pathways are always activated in glioma cells and GSCs, we hypothesize that CDH1 and Nocth-1 could be the direct targets of miR-92a." (PMID 27801803, 2016). "In addition, a markedly negative correlation between the expression of miR-92a-3p and CDH1 and Notch-1 was found in glioma cells and GSCs specifically." (PMID 27801803, 2016). "Furthermore, forced expression of CDH1 could mimic the inhibitory role of miR-92a-3p in glioma cell metastasis." (PMID 27801803, 2016). "qRT-PCR showed that CDH1 and TJP1/ZO-1 levels were lower than controls, indicating a reduced epithelial phenotype in higher-grade gliomas." (PMID 40679044, 2025). "It has been observed that FOXD2-AS1 long non-coding RNA (lncRNA) induced glioma cell proliferation and EMT by CDH1, CDH2, and VIM regulations through miR-506-5p sponging." (PMID 37051101, 2023). "Additionally, somatic mutations in KMT2C (FDR = 0.046) and CDH1 (FDR = 0.045) were found to be significantly associated with later-onset BRCA, while those in EGFR (FDR = 1.34E-7) and IDH1 (FDR = 1.34E-7) were found to be significantly associated with later-onset gliomas." (PMID 34788626, 2021). "In glioma, miR-92a has been identified to accelerate proliferation, cell survival, and metastasis through regulating BCL2L11, cadherin 1 (CDH1, also known as E-cadherin) and the Akt/mechanistic target of rapamycin kinase (mTOR) signaling." (PMID 33066509, 2020). "CDH1 expression is rare or absent in gliomas; CDH1 hypermethylation was found in 39.4% of GBM samples." (PMID 39061990, 2024). "Furthermore, in low-grade gliomas, including ODs, CDH1 is frequently altered by an alternative mechanism, i.e. hypermethylation of its promoter, resulting in down-regulated E-cadherin expression and worse outcome of patients." (PMID 33929593, 2021).
glioma (continued). "The quantitative real-time PCR method was used to evaluate mRNA expression of SEMA3(A-G), neuropilins (NRP1 and NRP2), plexins (PLXNA2 and PLXND1), cadherins (CDH1 and CDH2), integrins (ITGB1, ITGB3, ITGA5, and ITGAV), VEGFA and KDR genes in 59 II-IV grade glioma tissues." (PMID 33036421, 2020). "CDH1 expression is rare or absent in gliomas, and expression decreases with brain tumor grade." (PMID 39061990, 2024). "CDH1 expression in glial cells and gliomas has not been comprehensively studied." (PMID 33929593, 2021).